PSMB9 (proteasome 20S subunit beta 9)
Diseases named in the same sentence as PSMB9 in open-access papers (continued):
Sharing a sentence is not in itself a finding about the gene and the disease.
autoimmune disease (6 papers, 2009 to 2025). A disorder resulting from loss of function or tissue destruction of an organ or multiple organs, arising from humoral or cellular immune responses of the individual to their own tissue constituents. "Located within the HLA class II region, the PSMB9 gene harbors a functional missense SNP, rs17587, which has been previously associated with an increased risk of autoimmune diseases, including T1DM, particularly in Caucasian and Asian populations." (PMID 41441015, 2025). "PSMB9 plays a crucial role in various diseases, including neurodegenerative diseases, malignant tumors, and autoimmune diseases." (PMID 41425573, 2025). "A variety of studies have demonstrated that PSMB9 dysregulation contributes to autoimmune diseases, such as SS, rheumatoid arthritis, systemic lupus erythematosus (SLE) and dermatomyositis." (PMID 37153570, 2023). "Taken together, these findings show that PSMB9, CD74, and HLA-F all play important roles in presenting antigens and triggering autoimmune diseases." (PMID 37153570, 2023). "Immunoproteasome inhibitors have been shown to ameliorate symptoms in preclinical models of different autoimmune diseases, and KZR-616, a drug targeting both PSMB8 and PSMB9, has been tested in a Phase II trial of systemic lupus erythematosus." (PMID 37581620, 2023).
multiple myeloma (6 papers, 2017 to 2025). "RAC2 and PSMB9 have been revealed to be associated with disease development from MGUS to multiple myeloma and our analysis suggested that they might also be related to multiple myeloma rapid progression, supported by both scRNA-seq and CITE-seq." (PMID 36969740, 2022). "In myeloma, shared SNPs in PSMB6 and PSMB9 were associated with a decreased response to bortezomib therapy, without affecting survival, demonstrating how germline variation can influence IP-related therapeutic effects." (PMID 41293269, 2025). "In summary, previous studies indicated RAC2 and PSMB9 are associated with disease development from MGUS to multiple myeloma and our analysis suggested that they might also be related to multiple myeloma progression." (PMID 36969740, 2022). "We also found that RAC2 and PSMB9 are upregulated in NK cells in FPs relative to NPs at transcriptional level, which could potentially serve as multiple myeloma progression markers." (PMID 36969740, 2022). "PSMB8 and PSMB9 are the targets of Carfilzomib, a proteasome inhibitor for multiple myeloma." (PMID 29321020, 2018).
virus infection (6 papers, 2015 to 2025). "Secondly, the proteasome component PSMB9 converts the proteasome complex to an immunoproteasome by causing changes in proteolytic activity that generate T-cell epitopes presented on MHC class I molecules to CD8+T-cells, a central mechanism in the defense to viral infection." (PMID 28934294, 2017). "Of note, immunoproteasome subunit beta types PSMB8, PSMB9, and PSMB10, together with the PSME2 subunit of the immunoproteasome specific regulatory 11S cap structure, strongly indicated increased levels of immunoproteasomes with progressing virus infection." (PMID 37112941, 2023). "While we found that stimulation with exogenous IFNs could induce PSMB8, PSMB9 and PSMB10 expression in both cell lines, neither could produce the cytokines upon virus infection." (PMID 40872920, 2025).
Autoimmunity (5 papers, 2009 to 2025). The occurrence of an immune reaction against the organism's own cells or tissues. "The enrichment and burden tests performed in comparison with a control group underline that the products of expression by the variants involved belong to the autoimmunity and immune regulation pathways (i.e., SPINK5, PTPN22 and PSMB9)." (PMID 40725177, 2025).
colorectal cancer (5 papers, 2020 to 2025). A primary or metastatic malignant neoplasm that affects the colon or rectum. "Most of the PSMB1-10 genes were upregulated in adenomas and cancer compared to normal tissue, however only expression of the PSMB9 (encodes immune subunit β1i) was significantly higher in colorectal cancer compared to non-malignant adenomas." (PMID 38774235, 2024). "On the other hand, PSMB9 (LMP2, PSMB6i, β1i) was found to be frequently expressed in colorectal cancers, although no clear clinico-pathological correlations were apparent with its levels." (PMID 32850906, 2020). "Most of the PSMB1-10 genes were revealed to be upregulated in adenomas and cancer compared to normal tissue; however, only the expression of PSMB9, encoding immune subunit LMP2 (β1i), was significantly higher in colorectal cancer compared to nonmalignant adenomas." (PMID 40918453, 2025).
hepatocellular carcinoma (5 papers, 2008 to 2022). A malignant tumor that arises from hepatocytes. "IRF1, PSMB9, TAP1, ETV7, and PSMB10 were related to CD8+ T cell infiltration proportion in thyroid carcinoma, breast invasive carcinoma, head and neck squamous cell carcinoma, hepatocellular carcinoma, lung adenocarcinoma, and skin cutaneous melanoma." (PMID 33330025, 2020).
systemic lupus erythematosus (5 papers, 2009 to 2024). An autoimmune multi-organ disease typically associated with vasculopathy and autoantibody production. "Although there are very few reports about the role of PSMB9 in the onset and progression of RA and pSS, PSMB9 has recently been shown to be connected to a variety of immune-related diseases, such as dermatomyositis and systemic lupus erythematosus." (PMID 38359008, 2024). "For example, PSMB9 in systemic lupus erythematosus (SLE) and TRIM29 in SCC were obtained through proteomic screening, and further functional studies were conducted precisely." (PMID 36338621, 2022).
atherosclerosis (4 papers, 2024 to 2025). A disease characterized by the build-up of fatty material and calcium deposition in the arterial wall resulting in partial or complete occlusion of the arterial lumen. "The long non-coding RNA PSMB8-AS1 induces the expression of PSMB9 (LMP2), markedly increasing ICAM1 and VCAM1 levels in endothelial cells, which strengthens monocyte adhesion to the endothelium and intensifies vascular inflammation and atherosclerosis." (PMID 40855068, 2025). "For instance, the lncRNA PSMB8-AS1 is markedly elevated in human atherosclerotic plaques and promotes vascular inflammation and atherosclerosis by regulating the NONO/PSMB9/ZEB1 axis, demonstrating that it is possible to develop lncRNA-based strategies to combat cardiovascular disease." (PMID 41219994, 2025).
autoimmune hypothyroidism (4 papers, 2009 to 2024). "For example, DXO (celiac disease-related gene) and PSMB9 (alopecia areata-related gene) could modulate CDSN (autoimmune hypothyroidism-, psoriasis-, asthma-, and Graves’ disease-related gene) expression." (PMID 39009607, 2024).
bladder cancer (4 papers, 2020 to 2023). "However, despite these studies, research on PSMB8/PSMB9 loci concerning genetic risks in bladder cancers still needs to be completed." (PMID 36937130, 2023). "The present study exploited a variety of bioinformatic analyses to identify the PSMB8/PSMB9 immunoproteasomes and their co-expressed genes, which may be supported for the early diagnosis and prevention of bladder carcinoma." (PMID 36937130, 2023).
colon cancer (4 papers, 2017 to 2025). "Methylation-specific PCR analysis of the PSMB9 gene in the eight colon cancer cell lines investigated showed that it was unmethylated both in the untreated and 5-AC treated cell lines." (PMID 28622390, 2017). "Similarly, PSMB9 was downregulated significantly in all 8 of the colon cancer cell lines we tested compared to normal colon." (PMID 28622390, 2017).
Immunodeficiency (4 papers, 2021 to 2024). Failure of the immune system to protect the body adequately from infection, due to the absence or insufficiency of some component process or substance. "In this work, we identify a de novo PSMB9 heterozygous missense variant, G156D, in two unrelated Japanese patients with manifestations, including autoinflammation and immunodeficiency, which are similar to, but distinct from those of PRAAS patients." (PMID 34819510, 2021). "Immunodeficiency as well as proteasome defects, observed in two patients, were recapitulated in mice carrying the heterozygous PSMB9 G156D mutation." (PMID 34819510, 2021). "Recent studies have reported that the mutation in PSMB9 causes immunodeficiency phenotypes." (PMID 35393946, 2022). "Thus, although it remains unclear at present why PSMB9 G156D leads to immunodeficiency, mice with PSMB9 G156D mutation are a faithful model for analyzing proteasome defects." (PMID 34819510, 2021). "Genes involved in antigen processing and presentation, such as transporter 1 (Tap1), which is involved in antigen processing, and proteasome subunit‐β type‐9 (Psmb9), have been shown to play potential roles in a variety of immune diseases." (PMID 39295096, 2024). "Effects of PSMB10 G209W to induce immunodeficiency seem milder than those of PSMB9 G156D." (PMID 34819510, 2021). "Although the detailed molecular mechanisms are still unknown, it can be assumed that PSMB9 G156D and PSMB10 G209W should lead to defective interaction of two β rings and impaired formation of the 20S complex thereby causing immunodeficiencies." (PMID 34819510, 2021). "We describe a de novo heterozygous missense variant, p.G156D, in PSMB9 coding an immunoproteasome subunit, β1i, in two unrelated patients that manifest characteristic autoinflammation, similar to, but distinct from so far described PRAAS, with immunodeficiency." (PMID 34819510, 2021). "PSMB9 G156D mutant mice are useful to clarify not only the pathogenesis of proteasome dysfunctions but also homeostatic roles of immunoproteasome and to develop effective therapeutic maneuvers for PRAAS and immunodeficiency." (PMID 34819510, 2021).
sarcoidosis (4 papers, 2015 to 2025). Sarcoidosis is a multisystemic disorder of unknown cause characterized by the formation of immune granulomas in involved organs. "They demonstrated increased immunoreactivity of PSMB8 and PSMB9 in sarcoidosis lungs, primarily in epithelial cells and granulomas." (PMID 27460362, 2016). "Reanalysis of a sarcoidosis scRNA-seq dataset revealed that, similar to NL and NXG, sarcoidosis lesional fibroblasts expressed high levels of MHC (e.g., HLA-B and HLA-DRA), CD74, PLOD2, STAT1, TNC, PRSS23, PSMB9, and CXCL9." (PMID 39989459, 2025). "PSMB9, a gene downstream of STAT1, which is known to integrate with IFNG and to play a proteolytic role in MHC1 antigen presentation, has been reported to be upregulated in sarcoidosis." (PMID 36203777, 2022).
asthma (3 papers, 2020 to 2024). "In the case of PSMB9, while the coding region of the gene has 14 variants (item 3), only a single SNP (rs17587, P-value 7.26 × 10−7) is statistically significant for the association with asthma." (PMID 39406500, 2024). "Based on comprehensive genomics analyses, we found 31 genes with multiple eSNPs to be convincing candidates for childhood-onset asthma risk; such as, PSMB9 (cis-rs4148882 and cis-rs2071534) and TAP2 (cis-rs9267798, cis-rs4148882, cis-rs241456, and trans-10,447,456)." (PMID 32867763, 2020). "We illustrate the results in asthma for the PSMB9 gene (proteasome 20S subunit beta 9) that is ranked fourth in the male-dependent gene list." (PMID 39406500, 2024). "An analytical view of the PSMB9 gene in the context of asthma is shown via the population partition view by gene." (PMID 39406500, 2024). "Based on multiple lines of evidence, we highlighted 31 genes including PSMB9 and TAP2 with multiple eSNPs as childhood-onset asthma-associated causative candidates." (PMID 32867763, 2020). "We noticed that the eSNP of rs4148882 has cis-regulatory roles in influencing both PSMB9 and TAP2 expression, indicating that these two genes may have convergent effects on childhood-onset asthma susceptibility, which is in line with the findings in our GeneMANIA-based PPI network analysis." (PMID 32867763, 2020). "The genes of HLA-DRB5, HLA-DQA1, HLA-DPB1, CTSW, PSMB9, and TAP2 have the most number of edges with both predicted genes and childhood-onset asthma-related genes." (PMID 32867763, 2020).
diabetes (3 papers, 2021 to 2023). "Diseases associated with the PSMB9 gene in GWAS datasets from the DISEASES Experimental Gene-Disease Association Evidence Scores dataset revealed a potential association between PSMB9 and type 1 diabetes mellitus with a standardized value of 1.20753." (PMID 36527108, 2022).
Graves disease (3 papers, 2009 to 2024). Graves' disease is an autoimmune disorder that leads to overactivity of the thyroid gland (hyperthyroidism).It is caused by an abnormal immune system response that causes the thyroid gland to produce too much thyroid hormones. "DNA from 306 Caucasian patients with Graves' disease and 364 Caucasian control subjects were investigated for the distribution of an R/H polymorphism in the PSMB9 gene and a G/T polymorphism in the PSMB8 gene." (PMID 24490108, 2013). "No preferential allelic transmission occurred from heterozygote parents to offspring at either locus, suggesting that the association of the R/H polymorphism at codon 60 of PSMB9 with Graves' disease is due to linkage disequilibrium with the associated HLA haplotype." (PMID 24490108, 2013).
influenza (3 papers, 2014 to 2024). An acute viral infection of the respiratory tract, occurring in isolated cases, in epidemics, or in pandemics; it is caused by serologically different strains of viruses (influenzaviruses) designated A, B, and C, has a 3-day incubation period, and usually lasts for 3 to 10 days. "STAT1, TAP1, PSMB9, and PSME2, which are up-regulated preferentially by IFN-γ, were overexpressed only in influenza-specific cluster 1 (blue)." (PMID 32651212, 2020).
type 1 diabetes (3 papers, 2009 to 2022). "Besides, Phenotypes associated with the PSMB9 gene by text-mining GWAS publications from the HuGE Navigator Gene-Phenotype Associations dataset also suggested the potential association between PSMB9 mutations and type 1 diabetes." (PMID 36527108, 2022).
vitiligo (3 papers, 2009 to 2021). Generalized well circumscribed patches of leukoderma that are generally distributed over symmetric body locations and is due to autoimmune destruction of melanocytes. "In conclusion, the TAP1-rs1135216 and PSMB9-rs17587 variants are significantly associated with vitiligo, and even one copy of these mutant alleles can influence the risk among Saudis." (PMID 25548428, 2014). "The TAP1-rs1135216 and PSMB9-rs17587 mutant alleles were strongly associated with vitiligo, with odds ratios showing five fold and two fold risks (P < 0.0001 and P = 0.007, resp)." (PMID 25548428, 2014). "The TAP1 637G and PSMB9 60H mutant alleles were found to significantly increase the risk of vitiligo (fivefold and twofold, resp)." (PMID 25548428, 2014). "We evaluated whether TAP1-rs1135216 (p.637D>G) and PSMB9-rs17587 (p.60R>H) were significantly associated with the risk and severity of vitiligo among Saudi patients." (PMID 25548428, 2014). "An earlier study in Caucasians revealed a significant association between vitiligo and TAP1-rs1135216 (P = 0.0034) but a nonsignificant result between vitiligo and PSMB9-rs17587 (P = 0.11)." (PMID 25548428, 2014).
acute myeloid leukemia (2 papers, 2017 to 2026). Acute myeloid leukemia (AML) is a group of neoplasms arising from precursor cells committed to the myeloid cell-line differentiation. "These subnetworks included hub genes such as IFIT1, PSMB9, and HLA-B, which are known to be associated with immune evasion and drug resistance in acute myeloid leukemia." (PMID 42123467, 2026).
benign leiomyoma (2 papers, 2021 to 2022). "Lack of PSMB9 was reported to trigger the malignant transformation from benign leiomyoma to uterine leiomyosarcoma 86-88." (PMID 35693739, 2022).
celiac disease (2 papers, 2017 to 2024). An autoimmune genetic disorder with an unknown pattern of inheritance that primarily affects the digestive tract. "The proteomic analysis demonstrated that DXO (celiac disease- and T1D-related gene) and PSMB9 (alopecia areata-related gene) significantly altered the blood expression of CDSN, hinting that there might be a network of mutual regulatory mechanisms between these autoimmune-related genes." (PMID 39009607, 2024).
liver cancer (2 papers, 2021 to 2025). An epithelial or non-epithelial malignant neoplasm that arises from the liver. "The differences in protein levels of C1QC, CD3D, GZMA, and PSMB9 in different liver cancer stages were determined using immunohistochemistry." (PMID 34124275, 2021).
myositis (2 papers, 2014 to 2015). "Relative quantification of proteasomal subunit expression by real time RT-PCR revealed a myositis related significant increase of at least one of the immunoproteasomal subunits PSMB8, PSMB9 and/or PSMB10 in all investigated cellular subsets except CD4+." (PMID 25098831, 2014).
non-small cell lung carcinoma (2 papers, 2023 to 2025). A group of at least three distinct histological types of lung cancer, including non-small cell squamous cell carcinoma, adenocarcinoma, and large cell carcinoma. "A small group study found high PSMB9 levels related to durable clinical benefit after anti-PD1 treatment in non-small-cell lung cancers (NSCLCs), suggesting that PSMB9 could serve as a predictive biomarker for identifying patients likely to benefit from immunotherapy." (PMID 41020834, 2025).
ulcerative colitis (2 papers, 2010 to 2022). An inflammatory bowel disease involving the mucosal surface of the large intestine and rectum. "To confirm these data, we evaluated PSMB9 protein expression on tissue specimens of a cohort of ulcerative colitis (UC) patients and healthy controls (HC) collected at our institute." (PMID 36430249, 2022).
anxiety disorder (1 paper, 2024). A category of psychiatric disorders which are characterized by anxious feelings or fear often accompanied by physical symptoms associated with anxiety. "In addition, Psmb9 rs1043307 was positively correlated with anxiety disorders in patients with major depressive disorder comorbidities, although this result was not significant after adjusting for multiple comparisons." (PMID 39295096, 2024).
B-cell neoplasm (1 paper, 2025). A group of heterogeneous lymphoid tumors generally expressing one or more B-cell antigens or representing malignant transformations of B-lymphocytes. "Genetic alteration analysis revealed that PSMB9 is predominantly amplified in most cancers, while mature B-cell neoplasms exhibit a high rate of deep deletions, suggesting distinct selective pressures across tumor types." (PMID 41020834, 2025). "Genetically, PSMB9 alterations vary by cancer type, with amplification predominating in most tumors and deep deletions in mature B-cell neoplasms, while epigenetically, it correlates with RNA modification pathways, suggesting layered regulatory mechanisms." (PMID 41020834, 2025). "Mutation spectrum analysis based on the TCGA pan-cancer dataset revealed that the proportion of PSMB9 alterations was highest in mature B-cell neoplasms, approximately 8%, with deep deletion being the predominant type, accounting for about 3/4 of all alterations." (PMID 41020834, 2025).
breast tumor (1 paper, 2024). "As a proof of concept, B2m, Jak1, and Psmb9 single gene KOs were generated using the murine EMT6 breast tumor model to promote PD-1 or PD-L1 ICB resistance." (PMID 38427670, 2024).
Ebola (1 paper, 2025). "Correspondingly, antigen presentation ISGs (HLA-B, PSMB8, PSMB9, and TAP1102) were not markedly induced by Ebola, although they were upregulated in response to other viruses." (PMID 41279810, 2025).
Hepatitis (1 paper, 2024). Inflammation of the liver. "Upregulated ISGs (ISG20, IFI16, TAP2, GBP1, PSMB9) in the hepatitis phase were associated with T cell and macrophage infiltration and positively correlated with ALT levels." (PMID 39135698, 2024).